ATG4B (autophagy related 4B cysteine peptidase)
Diseases named in the same sentence as ATG4B in open-access papers (continued):
Sharing a sentence is not in itself a finding about the gene and the disease.
breast carcinoma (continued). "Unexpectedly, we found that ATG4B expression was elevated in HER2-positive breast cancer cells." (PMID 27556700, 2016). "To determine whether ATG4B inhibition under starvation triggers caspase-dependent cell death in HER2 positive breast cancer cells, we assessed executioner caspase activity levels using the luminescence-based Caspase-Glo assay." (PMID 27556700, 2016). "In addition to ATG4B, ATG4C has been implicated in breast cancer tumorigenesis." (PMID 40883962, 2025). "Silencing ATG4B significantly suppresses colorectal cancer (CRC) cell growth and enhances the sensitivity of HER2‐positive breast cancer cells to trastuzumab treatment." (PMID 40883962, 2025). "The specificity of G-cleave LC3B biosensor was confirmed via CRISPR gene editing of pivotal autophagy regulator ATG4B, yielding diminished luciferase activity in MDA-MB-231 breast cancer cells." (PMID 39736723, 2024). "Silencing ATG4B significantly suppresses cancer cell growth and synergizes the killing effects of trastuzumab in HER2-positive breast cancer cells." (PMID 31159487, 2019). "Our results suggest that ATG4B inhibition in combination with anti-HER2 therapy can be considered a potentially effective approach for both trastuzumab-sensitive and -resistant breast cancers." (PMID 27556700, 2016). "We here concluded that autophagy induced by SAHA in breast cancer cells is involved in TRAIL DR5, and this induction may be related to the increased catalytic activity of ATG4B (or other ATG molecules with similar functions, such as ATG9B)." (PMID 29018571, 2017). "We further evaluated the function of ATG4B in these cells and found that HER2-positive breast cancer cells, but not HER2-negative breast cancer cells required ATG4B to survive under stress." (PMID 27556700, 2016). "We compared basal levels of ATG4B protein expression in five HER2 positive and five HER2 negative breast cancer cell lines, and found that ATG4B levels were significantly (p<0.0001) elevated in HER2 positive cells." (PMID 27556700, 2016). "We showed that HER2-positive cells, but not HER2-negative breast cancer cells, require ATG4B to survive under stress." (PMID 27556700, 2016). "Here, the context-dependent role of ATG4B was observed in different breast cancer subtypes and linked to autophagy: HER2-positive, as opposed to HER2-negative, breast cancer cells required ATG4B to upregulate pro-survival autophagy in response to starvation." (PMID 27556700, 2016). "Overexpression of ATG4A, but not ATG4B, in mammospheres reportedly contributes to breast cancer stem cell maintenance, owing to its importance in autophagosomal maturation." (PMID 25426560, 2015). "However, little is known about ATG4B expression and function in breast cancers, nor have the contexts been identified where ATG4B inhibition might be beneficial." (PMID 27556700, 2016). "In this study, it was shown that HER2-positive breast cancer cells, but not HER2-negative cells, required ATG4B for survival under stress conditions." (PMID 31878323, 2019). "Here we evaluated ATG4B protein expression in a panel of HER2 negative and HER2 positive breast cancer cell lines." (PMID 27556700, 2016). "However, the role of ATG4B and the effects of ATG4B inhibition in HER2-positive breast cancers have never been reported before." (PMID 27556700, 2016).
glioblastoma (13 papers, 2019 to 2025). The most malignant astrocytic tumor (WHO grade IV). "In cancers, ATG4B has been identified as a potential therapeutic target in a number of cancers, including colon, glioblastoma, osteosarcoma." (PMID 35184132, 2022). "Inhibition of ATG4B in a subset of glioblastoma that has increased ATG4B phosphorylation resulted in the suppression of the tumors in animal models." (PMID 31083460, 2019). "Additionally, ATG4B-targeted inhibition results in reduced autophagy flux and tumorigenicity in glioblastoma cells." (PMID 37724907, 2023). "Furthermore, MST4 can phosphorylate ATG4B at Ser383 to induce autophagy and resistance to radiotherapy in glioblastoma cells." (PMID 31771238, 2019). "Additionally, G1 phase arrest was observed in glioblastoma cells expressing the ATG4B C74A mutant." (PMID 40883962, 2025). "However, some corroboration with our conclusions comes from the cancer literature, where genetic ablation of ATG4B or NSC185058 treatment has been show to slow cell growth in glioblastoma, while ATG4B knockout resulted in impaired mTORC1 activity in several cancer cell lines." (PMID 38582781, 2024). "Silencing ATG4B also led to cell cycle arrest at the G1‐S phase transition in both CRC and glioblastoma cells." (PMID 40883962, 2025). "In glioblastoma stem cells, MST4 kinase was upregulated by irradiation, which leads to the increased phosphorylation of ATG4B, more autophagy flux in GSCs, support of stemness, and increased tumorigenicity in vivo." (PMID 39201332, 2024). "As KDELC2 induces autophagy via upregulating LC3B, p62, and Atg4B expression and 3-MA administration suppresses HUVEC proliferation, we demonstrated that KDELC2 promotes tumor angiogenesis via increasing glioblastoma cellular autophagy." (PMID 37107298, 2023). "In glioblastoma, inhibition of MST4 inactivated ATG4B thus inhibits cancer cell autophagy and tumorigenicity." (PMID 32742458, 2020). "A role for autophagy in glioblastoma multiforme (GBM) has been proposed, and it was shown that inhibition of ATG4B in combination with radiotherapy can slow tumour growth in intracranial GBM xenograft models." (PMID 31878323, 2019). "Furthermore, compared to the shLuc-transfected glioblastoma cells, lower ATG4B and higher p62 mRNA expressions were noted in the shKDELC2-transfected GBM8401 and U87 glioblastoma cells." (PMID 37107298, 2023).
osteosarcoma (12 papers, 2016 to 2025). A usually aggressive malignant bone-forming mesenchymal neoplasm, predominantly affecting adolescents and young adults. "In osteosarcoma, the use of ATG4B antagonists provided a benefit in reducing growth of osteosarcoma tumours." (PMID 31878323, 2019). "For example, NSC185058 was reported as an ATG4B inhibitor, which could suppress the growth of osteosarcoma tumors and enhance the anti-cancer activity of radiation therapy." (PMID 32532053, 2020). "ATG4B could act as a pro-tumorigenic gene in cancers expressing it at a high level, including osteosarcoma, CML, HER2-positive breast and colorectal tumor cells." (PMID 31083460, 2019). "This study suggested that silencing ATG4 family members (ATG4A, ATG4B, ATG4C, and ATG4D) led to an increased proportion of cells in the G1 phase in osteosarcoma cells." (PMID 40883962, 2025). "The osteosarcoma cell line U2OS, either overexpressing Flag-ATG4Bwt or Flag-ATG4BC78S, was used to confirm that Cys-78 of ATG4B facilitates redox regulation of its delipidation activity." (PMID 33686057, 2021). "NSC185058 directly binds to and inhibits ATG4B in vitro and reduces growth of SAOS osteosarcoma cells in vivo." (PMID 31878323, 2019).
chronic myeloid leukemia (10 papers, 2015 to 2023). "Furthermore, the knockdown of the expression ATG4B has been associated with a decrease in cell viability and proliferation propagation of chronic myeloid leukemia cells leading to an accumulation of expression LC3-II and p62/SQSTM1." (PMID 32882870, 2020). "Likewise, upregulated ATG4B is associated with drug resistance in CD34+ chronic myeloid leukemia (CML) patients." (PMID 31159487, 2019). "In chronic myeloid leukemia cells, the knockdown of ATG4B suppresses autophagy and reduces the survival of cells, which increases the sensitivity of cancer cells to chemotherapy treatment." (PMID 36980240, 2023). "In a study investigating chronic myeloid leukaemia cells, it was reported that ATG4B, ATG5, and Beclin-1 expression levels are significantly increased." (PMID 31878323, 2019). "ATG4B was identified as a direct target of miR-34a in chronic myelogenous leukemia (CML), and the knockdown of ATG4B in CML led to impaired autophagic flux with an increase in LC3II levels and accumulation of p62." (PMID 26313360, 2015). "In chronic myeloid leukemia (CML), inhibition of autophagy by silencing ATG7 or ATG4B curbs the expansion of CML CD34+ stem/progenitor cells." (PMID 37886168, 2023). "In chronic myeloid leukemia (CML) stem/progenitor cells, ATG4B was highly expressed and knockdown of ATG4B suppressed autophagy, reduced the survival of these cancer cells and sensitized them to chemotherapy treatment." (PMID 31083460, 2019).
hepatocellular carcinoma (10 papers, 2017 to 2025). A malignant tumor that arises from hepatocytes. "In hepatocellular carcinoma, phosphorylation of autophagy-associated gene ATG4B at Ser34 promotes the Warburg effect by inhibiting mitochondrial function and participating in metabolic reorganization." (PMID 32983963, 2020). "In various cancer types, ATG4B inhibitors have shown significant synergy with chemotherapeutic drugs, including Azalomycin F4a in gastric cancer cells, a specific ATG4B inhibitor named DC‐ATG4in in hepatocellular carcinoma cells, and tioconazole in CRC cells." (PMID 40883962, 2025). "ATG4B in hepatocellular carcinoma (HCC) cells is also phosphorylated by AKT Serin/Threonine Kinase 1 (AKT1)." (PMID 35456009, 2022). "For example, it promotes atg4b-mediated autophagy and attenuates sorafenib sensitivity in hepatocellular carcinoma cells; it regulates eIF4A3/MUC1/EGFR signalling and modulates the response of EGFR-mutant lung cancer to EGFR tyrosine kinase inhibitor resistance." (PMID 35359593, 2022). "CRNDE facilitates ATG4B-induced autophagy as well as weakens sorafenib sensitivity in hepatocellular carcinoma (HCC) cells." (PMID 37194105, 2023). "The long non-coding RNA (lncRNA) colorectal neoplasia differentially expressed (CRNDE) promotes the progression of hepatocellular carcinoma (HCC), but it is unclear whether the tumor-promoting effect of CRNDE is associated with the regulation of ATG4B and autophagy." (PMID 34409031, 2021). "Another report has shown that HSF1 upregulates the expression of ATG4B in hepatoma carcinoma cells by binding to the promoter region of the gene and consequently enhancing the epirubicin (EPI)-induced protective autophagy, which in turn promotes hepatocellular carcinoma (HCC) cell survival." (PMID 36598250, 2023).
gastric cancer (8 papers, 2021 to 2025). A primary or metastatic malignant neoplasm involving the stomach. "In our recent research, we confirmed that ATG4B is a novel RNA binding protein in the gastric cancer (GC) cell." (PMID 38803355, 2024). "Altogether, it is tentatively suggested that the PGD2/PTGDR2 signaling pathway may influence gastric cancer development by regulating the ubiquitination of ATG4B." (PMID 39777337, 2024). "Recently, we published our latest research in the journal AUTOPHAGY about promoting the anoikis of gastric cancer (GC) cells by enhancing the ubiquitin-dependent degradation of ATG4B." (PMID 38803355, 2024). "The methyltransferase MGMT inhibits the expression of ATG4B, thereby inhibiting autophagy and reducing the chemosensitivity of cisplatin in gastric cancer (GC)." (PMID 33604190, 2021).
lung carcinoma (7 papers, 2018 to 2025). "Similar results were seen in a K-Ras mutant lung cancer genetically engineered mouse model (GEMM) expressing dominant negative ATG4B." (PMID 31878323, 2019). "There is increasing evidence that modulation of ATG4B by either si/shRNA-mediated knockdown or the expression of a dominant negative construct results in a benefit in multiple cancer models, including breast, pancreatic and lung cancer." (PMID 31878323, 2019). "In a genetically-engineered mouse model of K-Ras-driven lung cancer, the expression of doxycycline-inducible dominant negative ATG4B C74A resulted in a strong reduction in lung cancer cell growth, suggesting that inhibition of ATG4B is a promising strategy for treatment of lung cancer." (PMID 31878323, 2019). "In lung cancer cell lines, SLC27A4 directly interacts with autophagy-related 4B cysteine peptidase (ATG4B)." (PMID 30388870, 2018). "Taken together, our results demonstrate that ATG4B is required for anabolic behavior in NSCLC, indicating that the autophagic cascade may be a required input for mTORC1 activity and cellular anabolism in lung cancer." (PMID 41065169, 2025). "Finally, in human lung cancer cells, ATG4B directly interacted with soluble carrier family 27 member 4 (SLC27A4) to form a SLC27A4/ATG4B complex, and knockdown of SLC27A4 could decrease the ATG4B level, thus enhancing the therapeutic efficiency of chemotherapeutic drugs." (PMID 31083460, 2019).
colon cancer (6 papers, 2016 to 2022). "Importantly, ATG4B expression in colon cancer cells (SW620, HCT116, and RKO) was indeed higher than that in normal colon cell (NCM460)." (PMID 36539845, 2022). "Our previous studies revealed that ATG4B is a potential therapeutic target in colon cancer." (PMID 35184132, 2022). "In addition, ATG4B overexpression conferred cancer drug resistance while its inhibition markedly sensitized tumors to chemotherapy in lung cancer, colon cancer, and chronic myeloid leukemia." (PMID 35184132, 2022). "However, BIX01294 induced changes could be cell-type specific, as in human colon cancer HCT116 cells the expression of LC3B, ATG9A, ATG4A, but not ATG4B/C, ATG7, BECN1, WIPI1 was increased after BIX01294 treatment." (PMID 27934912, 2016).
pancreatic cancer (6 papers, 2016 to 2024). "In another study, autophagy inhibition was determined to decrease the growth of pancreatic tumor in the dominant-negative Atg4b mouse model, which is also involved in the macrophage-mediated mechanisms." (PMID 35935871, 2022). "There is strong evidence indicating that pancreatic cancer cells are vulnerable to inhibition of ATG4B." (PMID 34868951, 2021). "Evidence has shown that mice with pancreatic tumor carrying a dominant negative ATG4B mutant displayed a significantly higher number of CD68+ macrophages in the tumors compared to mice carrying wild-type ATG4B." (PMID 38627815, 2024). "A markedly high number of copy number deletions were also observed for the PIK3C3 gene in Pancreatic cancer (24%), whereas copy number amplifications for ATG9B (17%), ATG4B (16%) and MAP1LC3C (13%) were commonly found." (PMID 27256984, 2016).
prostate carcinoma (6 papers, 2015 to 2024). A carcinoma that arises from epithelial cells of the prostate gland. "The authors proposed that down-regulating ATG4B expression through miRNA34A made prostate cancer cells more prone to chemoresistance and survival under stress." (PMID 31878323, 2019). "This is in contrast to another study that suggested miRNA34A-mediated chemoresistance in prostate cancer cells is—at least in part—mediated by reduced ATG4B expression." (PMID 31878323, 2019). "In this study, it was suggested that higher levels of ATG4B are essential for maximal growth of prostate cancer cells." (PMID 31878323, 2019). "ATG4B is an androgen receptor responsive gene that correlates with disease progression in prostate cancer." (PMID 31878323, 2019). "Another study suggested that the role of ATG4B in prostate cancer is cell type-, treatment-, and context-dependent, showing that the use of a dominant negative construct can either enhance the effect of chemotherapy or contribute to treatment resistance." (PMID 31878323, 2019). "Another study showed that siRNA-mediated knockdown of ATG4B in prostate cancer cells resulted in increased apoptosis, further supporting the notion that inhibition of ATG4B may be beneficial for reducing prostate cancer growth." (PMID 31878323, 2019). "In cancer cells overexpressing the miR-34a show reduced expression of autophagy-related proteins, such as ATG4B, Beclin-1 and LC3B II/I in prostate cancer cells by p-AMPK down-regulation as well as up-regulation of p-mTOR." (PMID 35193115, 2022). "However, miR-34a had only a minor affect in decreasing ATG4B expression, suggesting that unlike CML cells, ATG4B is not likely a target of miR-34a in prostate cancer cells." (PMID 26313360, 2015).
diabetic kidney disease (5 papers, 2022 to 2025). Progressive kidney disorder caused by vascular damage to the glomerular capillaries, in patients with diabetes mellitus. "Aif1 promotes inflammation and OS in diabetic nephropathy through the miR-34a/ATG4B pathway." (PMID 36826575, 2023). "Furthermore, in this study, we demonstrated for the first time that AIF-1 regulated the level of inflammation, oxidative stress, and autophagy in glomerular endothelial cells through miR-34a/ATG4B pathway in diabetic kidney disease." (PMID 36345369, 2022). "Besides, miR-34a was elevated in renal tissue of diabetic kidney disease (DKD) and increased the levels of ROS and inflammation in human renal glomerular endothelial cells by inhibiting the expression of autophagy-related gene 4B (ATG4B), which might contribute to the pathogenesis of DKD." (PMID 37660030, 2023).
glioma (5 papers, 2019 to 2025). A benign or malignant brain and spinal cord tumor that arises from glial cells (astrocytes, oligodendrocytes, ependymal cells). "Using siRNAs against autophagy-related genes ATG7, ATG4b, we assessed the viability of both mouse and human glioma cells treated with radiation." (PMID 40964044, 2025). "The Kaplan-Meier analysis showed that higher expression levels of ATG4B were correlated to shorter OS time in gliomas using both the CGGA and TCGA databases." (PMID 35341001, 2022). "The further analysis showed that ATG4B was significantly upregulated and correlated to shorter OS time in gliomas using both the CGGA and TCGA databases." (PMID 35341001, 2022). "Huang and colleagues suggested that MST4 protein level within glioma cells increased after X-ray irradiation, and MST4 enhanced its activity by the phosphorylation of ATG4B, an autophagy-related protein, for inducing autophagy while reducing glioma cell radiosensitivity." (PMID 34528498, 2021). "To this end, we used siRNAs targeting ATG4b and ATG7 and assessed the viability of mIDH1 glioma NS treated in combination with radiation." (PMID 40964044, 2025). "In addition, we evaluated the impact of the molecular inhibition of autophagy on glioma cells’ radio-responses through siRNAs against autophagy-related genes ATG7 and ATG4b and through the knockdown of ATG7 in mouse glioma cells." (PMID 40964044, 2025). "Although the roles of ATG4C and ATG4D in autophagy are less well‐characterized compared to ATG4A and ATG4B, knockdown of ATG4C has been shown to induce cell cycle arrest at the G1 phase and ROS‐mediated apoptosis in glioma cells, likely through suppression of autophagy." (PMID 40883962, 2025).